ARMC7 (armadillo repeat containing 7)
Description:
As a component of the minor spliceosome, involved in the splicing of U12-type introns in pre-mRNAs.
Synonyms: FLJ22160
Tractability: Small molecule: a structure with a bound ligand is known.
Gene: Protein-coding gene on chromosome 17 (75,109,952 to 75,130,272, forward strand). Ensembl gene ENSG00000125449.
Subcellular location (Human Protein Atlas): Cytosol
Gene Ontology:
Molecular function: protein binding
Biological process: mRNA splicing, via spliceosome
Cellular component: cytosol; U12-type catalytic step 2 spliceosome
Genetic constraint (gnomAD): Loss-of-function variants: 9 observed, 15.62 expected, observed/expected ratio (o/e) 0.58, 90% interval 0.35 to 1. The upper end of that interval is the gene's LOEUF score, 1, which puts it in group 4 of 6, group 1 being the genes least tolerant of losing a copy. Missense variants: 262 observed, 268.87 expected, observed/expected ratio (o/e) 0.97, 90% interval 0.88 to 1.08. Synonymous variants: 125 observed, 127.18 expected, observed/expected ratio (o/e) 0.98, 90% interval 0.85 to 1.14.
Homologues: Orthologues: chimpanzee ARMC7 (100% identical), macaque ARMC7 (97% identical), dog ARMC7 (88% identical), guinea pig ARMC7 (86% identical), mouse Armc7 (84% identical).
Diseases named in the same sentence as ARMC7 in open-access papers:
ARMC7 is named in the same sentence as 5 diseases in open-access papers, as found by Europe PMC text mining. Sharing a sentence is not in itself a finding about the gene and the disease. The quoted sentences say what the papers report.
breast carcinoma (1 paper, 2018). "Within cancer research, ARMC7 has been the subject of research as a prognostic marker for breast cancer, but to our knowledge, no studies have shown a relationship between the gene and boar taint." (PMID 29438444, 2018).
cervical cancer (1 paper, 2025). A primary or metastatic malignant neoplasm involving the cervix. "ARMC7 is one of the seven differentially expressed mRNAs included in a prognostic signature for predicting recurrence and DFS in cervical cancer patients." (PMID 41373732, 2025).
diffuse large B-cell lymphoma (1 paper, 2025). "High plasma levels of a five-gene signature, which included ARMC7, were significantly associated with inferior overall survival in diffuse large B-cell lymphoma patients, independent of the National Comprehensive Cancer Network International Prognostic Index score." (PMID 41373732, 2025).
cancer (2 papers, 2018 to 2021). A tumor composed of atypical neoplastic, often pleomorphic cells that invade other tissues. "ARMC7 encodes an essential nuclear protein and has been found to be amplified in several cancer tissues and cell lines." (PMID 29438444, 2018). "ARMC7 was found to be amplified across several cancer tissues and cell lines." (PMID 34550275, 2021).
nervous system disorder (1 paper, 2022). A non-neoplastic or neoplastic disorder that affects the brain, spinal cord, or peripheral nerves. "On the other hand, the ARMC proteins including ARMC4, ARMC5, ARMC6, ARMC7, ARMC8, ARMC10, and ARMCX3 regulate the Wnt signaling pathway leading to specific nervous system disorders." (PMID 36553564, 2022).